MAP1LC3A (microtubule associated protein 1 light chain 3 alpha)
Description:
Ubiquitin-like modifier involved in formation of autophagosomal vacuoles (autophagosomes). While LC3s are involved in elongation of the phagophore membrane, the GABARAP/GATE-16 subfamily is essential for a later stage in autophagosome maturation. Through its interaction with the reticulophagy receptor TEX264, participates in the remodeling of subdomains of the endoplasmic reticulum into autophagosomes upon nutrient stress, which then fuse with lysosomes for endoplasmic reticulum turnover.
Synonyms: MAP1BLC3; MAP1ALC3; LC3; LC3A; ATG8E
Tractability: Small molecule: a structure with a bound ligand is known. PROTAC: ubiquitination databases record sites on it; its protein half-life has been measured; a small molecule that binds it is known.
Gene: Protein-coding gene on chromosome 20 (34,546,838 to 34,560,357, forward strand). Ensembl gene ENSG00000101460.
Subcellular location: Cytoplasmic vesicle, autophagosome membrane; Endomembrane system; Cytoplasm, cytoskeleton
Subcellular location (Human Protein Atlas): Vesicles; Basal body; Cytosol
Pathways (Reactome):
Autophagy: Macroautophagy; PINK1-PRKN Mediated Mitophagy; Receptor Mediated Mitophagy
Gene Ontology:
Molecular function: phospholipid binding; protein binding; ubiquitin protein ligase binding; microtubule binding; phosphatidylethanolamine binding
Biological process: autophagosome assembly; autophagosome maturation; autophagy of mitochondrion; cellular response to starvation; macroautophagy; cellular response to nitrogen starvation; mitophagy; autophagy; cellular response to amino acid starvation; cellular response to copper ion; cellular response to hydrogen peroxide; cellular response to oxygen-glucose deprivation; JNK cascade; p38MAPK cascade; response to iron(II) ion; response to lead ion; response to nutrient levels; SMAD protein signal transduction
Cellular component: autolysosome; autophagosome; cytosol; endomembrane system; organelle membrane; autophagosome membrane; cytoplasm; cytoskeleton; glutamatergic synapse; late endosome; membrane; synapse
Genetic constraint (gnomAD): Loss-of-function variants: 10 observed, 13.1 expected, observed/expected ratio (o/e) 0.76, 90% interval 0.47 to 1.29. The upper end of that interval is the gene's LOEUF score, 1.29, which puts it in group 5 of 6, group 1 being the genes least tolerant of losing a copy. Missense variants: 138 observed, 155.56 expected, observed/expected ratio (o/e) 0.89, 90% interval 0.77 to 1.02. Synonymous variants: 63 observed, 60.46 expected, observed/expected ratio (o/e) 1.04, 90% interval 0.85 to 1.28.
Homologues: Orthologues: guinea pig MAP1LC3A (100% identical), mouse Map1lc3a (100% identical), rat Map1lc3a (100% identical), pig MAP1LC3A (99% identical), zebrafish map1lc3a (95% identical), tropical clawed frog map1lc3a (92% identical), chimpanzee MAP1LC3A (91% identical), macaque MAP1LC3A (91% identical), Caenorhabditis elegans lgg-2 (58% identical). Paralogues in human: MAP1LC3B (82% identical), MAP1LC3B2 (81% identical), MAP1LC3C (57% identical), GABARAPL2 (41% identical), GABARAPL1 (33% identical), GABARAP (31% identical).
Diseases named in the same sentence as MAP1LC3A in open-access papers:
MAP1LC3A is named in the same sentence as 416 diseases in open-access papers, as found by Europe PMC text mining. Sharing a sentence is not in itself a finding about the gene and the disease. The quoted sentences say what the papers report.
breast carcinoma (128 papers, 2008 to 2026). "MAP1LC3A is also an autophagy-associated protein that has been reported to be involved in the process of autophagy and is involved in the development of breast cancer." (PMID 37889013, 2023). "So far, among these 6 ARGs, Only TRIM21 and MAP1LC3A, as low-risk autophagy-related genes, have been studied in breast cancer or other cancers." (PMID 34001111, 2021). "In conclusion, we identified a novel autophagy-related prognostic risk model consisting of six encoding gene (VPS35, TRIM21, PRKAB2, RUFY4, MAP1LC3A and LARP1) in breast cancer." (PMID 34001111, 2021). "MAP1LC3A codes for a protein that is important in the autophagy process, and was found to be expressed at higher level in breast cancer tissues than in normal tissues." (PMID 28957356, 2017). "Similar, MAP1LC3A was the most valuable marker to follow up on breast cancer (METABRIC dataset)." (PMID 39859167, 2025). "Specifically, in breast cancer (BRCA) and head and neck squamous cell carcinoma (HNSC), PRKN, PINK1, and MAP1LC3A were downregulated, while SRC and BECN1 were upregulated." (PMID 39859167, 2025). "In this study, the prognostic risk model consisting of six ARGs (VPS35, TRIM21, PRKAB2, RUFY4, MAP1LC3A and LARP1) in breast cancer were identified." (PMID 34001111, 2021). "We examined this issue by reducing the prevalence of breast cancer samples (i.e., we only used a half number of breast cancer patients, including 606/1212 randomly selected patients), and we identified a new signature including 7 genes CDK1, AP1S1, CASP3, MAP1LC3A, SNCA, MAPT, and GSK3B." (PMID 38642129, 2024).
lung carcinoma (75 papers, 2012 to 2025). "MAP1LC3A expression is inversely correlated with the histological grade and aggressiveness of lung cancers." (PMID 37664173, 2023).
melanoma (74 papers, 2011 to 2025). A malignant, usually aggressive tumor composed of atypical, neoplastic melanocytes.
glioma (73 papers, 2009 to 2025). A benign or malignant brain and spinal cord tumor that arises from glial cells (astrocytes, oligodendrocytes, ependymal cells). "The expression of variant 1 in MAP1LC3A is commonly silenced at the transcriptional level in numerous cancer cell lines due to epigenetic changes, indicating that it may be implicated in the carcinogenesis of gastric cancer, osteosarcoma, and glioma." (PMID 35309911, 2022). "However, MAPK1 and MAP1LC3A had relatively low expression in glioma tissues." (PMID 35711838, 2022). "The expression of MAP1LC3A was reported to be suppressed in many tumor cell lines, suggesting that it may be involved in the carcinogenesis of multiple tumors, such as gastric cancer, esophageal squamous carcinoma, osteosarcoma, and glioma." (PMID 31844032, 2019).
osteosarcoma (50 papers, 2010 to 2025). A usually aggressive malignant bone-forming mesenchymal neoplasm, predominantly affecting adolescents and young adults. "Knockdown of SRMS in U2OS human osteosarcoma cells led to a depletion of LC3 (microtubule-associated protein 1 light chain 3 alpha), indicative of an increase in autophagic flux." (PMID 32545875, 2020). "Prior study has noted that MAP1LC3A expression was suppressed in many tumor cell lines, which suggested that it might be highly linked to the tumorigenesis of gastric cancer, esophageal squamous carcinoma, and osteosarcoma." (PMID 33178587, 2020).
colorectal cancer (49 papers, 2013 to 2025). A primary or metastatic malignant neoplasm that affects the colon or rectum. "Similarly, upregulation of MAP1LC3A in colorectal cancer is correlated with better outcomes, reinforcing the prognostic value of these markers." (PMID 39859167, 2025).
ovarian carcinoma (46 papers, 2012 to 2025). A malignant neoplasm originating from the surface ovarian epithelium. "Similarly, elevated expression of MAP1LC3A/LC3A, a protein required for autophagosome membranes, is associated with platinum resistance in ovarian cancer." (PMID 34645978, 2021).
viral infection (46 papers, 2012 to 2025). "As per viral infection, NIC and virus treated cells (at 48 h) also saw an up-regulation of GABARAPL1, MAP1LC3A, USP30, BMF, and TBK1; WDR81 was also down-regulated in the NIC and virus treatment at 48 h." (PMID 37901834, 2023).
diabetes (36 papers, 2013 to 2025). "Specifically in β-cells, TG-induced stress resulted in increased expression of ARID5B (part of demethylase complex), MAP1LC3A (Mitophagy), and CLIC1 (chloride channel) expression and decreased G6PC2 and HADH, which have been associated with diabetes." (PMID 38956087, 2024).
glioblastoma (36 papers, 2012 to 2025). The most malignant astrocytic tumor (WHO grade IV). "MAP1LC3A expression differed among classical, G-CIMP, mesenchymal, neuronal, and proneuronal subtypes in glioblastoma (GBM) but also among KIRC and STAD subtypes." (PMID 39859167, 2025).
Obesity (20 papers, 2015 to 2025). Accumulation of substantial excess body fat. "The detrimental effect of obesity on CAD appears to be primarily mediated by MAP1LC3A, ANGPTL4, RPS6KA1, PCSK9, ITPKA, and AGER." (PMID 38049831, 2023).
Hepatic steatosis (15 papers, 2016 to 2024). Steatosis is a term used to denote lipid accumulation within hepatocytes. "Both expression of MAP1LC3A and Beclin 1 in patient is exhibited much lower in immunostaining and Western blotting but not vanished indicating possible tendency of lipophagy in development of fatty liver disease." (PMID 32280452, 2020).
periodontitis (12 papers, 2012 to 2025). An acute or chronic inflammatory process that affects the tissues that surround and support the teeth. "The results pertaining to mitophagy-related markers indicated that the expression levels of mitophagy pathway-related genes (Bnip3 and Fundc1) and autophagy-related genes (Map1lc3a and Map1lc3b) were significantly upregulated in the periodontitis+TTM group when compared with the periodontitis group." (PMID 38892077, 2024).
triple-negative breast carcinoma (11 papers, 2017 to 2025). An invasive breast carcinoma which is negative for expression of estrogen receptor (ER), progesterone receptor (PR), and human epidermal growth factor receptor 2 (HER2). "Moreover, the low expression of MAP1LC3A elevates the risk of distant metastasis in triple-negative breast cancer." (PMID 34001111, 2021).
lung adenocarcinoma (9 papers, 2014 to 2025). A carcinoma that arises from the lung and is characterized by the presence of malignant glandular epithelial cells. "In addition, PRKN, PINK1 and MAP1LC3A, expression levels were positively correlated with the infiltration score, as well as the infiltration of various immune cells, including iTreg, effector memory, exhausted, Th1, and nTreg cells in lung adenocarcinoma (LUAD)." (PMID 39859167, 2025).
Parkinson disease (9 papers, 2014 to 2024). A progressive degenerative disorder of the central nervous system characterized by loss of dopamine producing neurons in the substantia nigra and the presence of Lewy bodies in the substantia nigra and locus coeruleus. "It has been shown that overexpression of miR-133a inhibits MPP+-induced autophagy (MAP1LC3A/MAP1LC3B, BECN1, NUP62) in a cellular model of Parkinson’s disease, and downregulation of miR-17-5p inhibits infarction-induced myocardial autophagy." (PMID 36324052, 2023).
Salmonella Infections (8 papers, 2014 to 2026). Infections with bacteria of the genus SALMONELLA. "Interestingly, the expression of microtubule-associated protein 1 light chain 3 alpha (LC3) increased in butyrate-treated macrophages due to mTOR inhibition during Salmonella infection." (PMID 33530627, 2021).
dementia with Lewy bodies (6 papers, 2012 to 2025). "Impaired autophagy in neurons through genetic disruption of MAP1LC3A/B along with ATG5/ATG7 induced neuropathologic features in dementia with Lewy bodies (DLB) patients." (PMID 33419148, 2021).
type 2 diabetes (5 papers, 2020 to 2025). "The increased risk of type 2 diabetes was significantly associated with the MAP1LC3A expression in various tissues such as the pancreas (Z = 2.4, Q = 0.008), skeletal muscle (Z = 2.5, Q = 0.006), adipose tissue (Z = 2.4, Q = 0.008), and whole blood (Z = 2.3, Q = 0.01)." (PMID 34575035, 2021). "Transcription factors co-regulating the pancreatic expression of EDEM2, MYH7B, MAP1LC3A, and CPNE1 genes that associated with type 2 diabetes have been predicted by the hTFtarget tool." (PMID 34575035, 2021). "The TWAS analysis has shown that the pancreatic expression of EDEM2, MYH7B, MAP1LC3A, and CPNE1 correlated to a carriage of T2D-associated alleles of GSS and GGT7 is associated with the genetic risk of type 2 diabetes." (PMID 34575035, 2021). "In addition, further TWAS analysis has revealed that the increased pancreatic expression of EDEM2, MYH7B, MAP1LC3A and decreased levels of CPNE1 are associated with the genetic risk of type 2 diabetes." (PMID 34575035, 2021). "Thus, the TWAS analysis allowed revealing the genetic association between the changes in pancreatic expression of genes such as EDEM2, MYH7B, MAP1LC3A, and CPNE1 and the risk of type 2 diabetes." (PMID 34575035, 2021).
rectal cancer (3 papers, 2014 to 2025). A primary or metastatic malignant neoplasm that affects the rectum. "In the present study, we aimed to determine the expression patterns, clinicopathological significance, and prognostic value of the autophagy marker microtubule-associated protein 1 light chain 3 alpha (LC3A)—an essential component of autophagic vacuoles—in rectal cancer." (PMID 40361494, 2025). "Here, we investigated the relationship between rectal cancer outcomes and expression patterns of microtubule-associated protein 1 light chain 3 alpha (LC3A), a marker protein for the essential cellular self-degradation mechanism known as autophagy, in tumors from 243 rectal cancer patients." (PMID 40361494, 2025).
sarcopenia (3 papers, 2019 to 2024). Progressive decline in muscle mass due to aging which results in decreased functional capacity of muscles. "Finally, age-related declines in autophagy-related proteins LC3 (MAP1LC3A) and ATG7 have previously been reported, and these declines are thought to contribute to sarcopenia." (PMID 33669246, 2021).
colon adenocarcinoma (2 papers, 2016 to 2021). "Our microarray data show DJ-1 mRNA expression was positively correlated with MAP1LC3A and MAP1LC3B expressions in tumor tissues from subjects with colon adenocarcinoma." (PMID 34439303, 2021). "The analysis results of GEPIA (Gene Expression Profiling Interactive Analysis) show DJ-1 mRNA expression was positively corrected with MAP1LC3A and MAP1LC3B expressions in tumor tissues of subjects with colon adenocarcinoma (R = 0.41 in both two)." (PMID 34439303, 2021).
coronary artery disease (2 papers, 2019 to 2025). "Rs2424994 in MAP1LC3A was associated with coronary artery disease (p-value = 5.8×10−6)." (PMID 30908504, 2019).
prostate adenocarcinoma (2 papers, 2015 to 2025). "In prostate adenocarcinoma (PRAD), OPTN, PRKN, BNIP3L, PINK1, and MAP1LC3A were significantly downregulated." (PMID 39859167, 2025).
uveal melanoma (1 paper, 2021). A melanoma derived from melanocytes of the uveal tract. "In uveal melanoma patients, autophagy-associated proteins MAP1LC3A and BECN1 are commonly upregulated and are related to tumor development which resulted in poor prognosis." (PMID 34426753, 2021).
infection (464 papers, 2008 to 2026). The state of being infected such as from the introduction of a foreign agent such as serum, vaccine, antigenic substance or organism. "Finally, a potential link between autophagy and disease was observed in a study of genetic polymorphisms linked to chronic Q fever, where SNPs in ATG5 and MAP1LC3A were more commonly associated with controls, suggesting that autophagy promotes infection or more severe disease." (PMID 37645379, 2023). "Our data show that the Ca2+-AMPK pathway is required for transcriptional activation of the essential autophagy genes Gabarap, Gabarapl1, Map1lc3a, and Foxo3 in the context of myeloid-specific Gabra4 signaling during infection." (PMID 40395295, 2023). "The results revealed that the relative expression of ULK2, SQSTM1, and MAP1LC3A was significantly higher in the virus group in comparison with the artificial seawater group at later time points of the experimental infection (18 to 30 hpi; p ≤ 0.05)." (PMID 35444958, 2022). "At 24 hpi, MAP1LC3A RNA expression in A3 cells was not affected by infection with either RVFV variant, whereas in Jar cells, wt RVFV-infected cells showed a 5.6-fold increase in MAP1LC3A RNA expression." (PMID 34835071, 2021). "Recently, circ_8521, a sponge for miR-324, has been reported to promote microtubule associated protein 1 light chain 3 alpha (LC3A) protein expression and autophagy in porcine cells via the circ_8521/miR-324/LC3A pathway, ultimately enhancing SVA infection." (PMID 40182764, 2025). "On the other hand, in the NH4Cl group, the relative expression of MAP1LC3A, ULK2, and SQSTM1 was higher at early (6 to 14 hpe) and late time points (18 to 30 hpe) of the experimental infection in comparison with the artificial seawater group (p ≤ 0.05)." (PMID 35444958, 2022). "Our study showed that the expression of autophagy-related genes ULK1, ATG13, ATG101, Beclin-1, ATG14, MAP1LC3A, and MAP1LC3B was significantly increased and that SQSTM1 was decreased in the muscle with pathogen infection." (PMID 33574492, 2021). "Map1lc3a was strongly expressed in epithelial cells, stromal cells, endothelial cells and pericytes, but this did not change with infection." (PMID 35903351, 2022).